FOXP2 (forkhead box P2)
Diseases named in the same sentence as FOXP2 in open-access papers (continued):
Sharing a sentence is not in itself a finding about the gene and the disease.
developmental verbal dyspraxia (29 papers, 2010 to 2024). "Of these, FOXP2 is acknowledged as a monogenic cause for specific Speech-Language disorder-1 (OMIM# 602081) and ATP2C2 as a susceptibility locus (OMIM % 606711) contributing in the etiology of DLD." (PMID 38298611, 2024). "Mutations in MET are a risk factor for ASD, and MET is also regulated by the transcription factor FOXP2, which causes developmental verbal dyspraxia when mutated." (PMID 36794006, 2020). "A previous study described a family with developmental verbal dyspraxia, where affected individuals had a loss of function mutation in the FOXP2 gene." (PMID 32246137, 2020). "The FoxP2 transcription factor and its target genes have been implicated in developmental brain diseases with a prominent language component, such as developmental verbal dyspraxia and specific language impairment." (PMID 29920554, 2018). "Most notably, the linkage peak spanning 7q22.3–q31.2 has a max LOD = 2.06 and contains the gene FOXP2—a causal gene for Childhood Apraxia of Speech." (PMID 27535846, 2016). "FOXP2 gene, which encodes a neurally expressed transcription factor, was discovered through linkage analysis of a large family who had developmental verbal dyspraxia (DVD) or childhood apraxia of speech (CAS)." (PMID 25178928, 2014). "Mutations in FOXP2 have been previously related to monogenic cases of developmental verbal dyspraxia." (PMID 20848658, 2010). "Members of the FOX family are involved in many diverse developmental pathways, and mutations in FOXP2 cause a distinct form of developmental verbal dyspraxia in the KE family, as previously discussed." (PMID 20345892, 2010). "Pathogenic variants of FOXP2 gene were identified first as a monogenic cause of childhood apraxia of speech (CAS), a complex disease that is associated with an impairment of the precision and consistency of movements underlying speech, due to deficits in speech motor planning and programming." (PMID 34490154, 2021). "A loss of paternal FOXP2 in children with developmental verbal dyspraxia." (PMID 24765219, 2013). "Although many cases of language impairment are multifactorial, mutations in a single gene on 7q31, FOXP2, have been shown to cause developmental verbal dyspraxia in a large pedigree, called the KE family, and a number of individual cases [reviewed in Fisher and Scharff (2009)]." (PMID 20345892, 2010). "Reduced functional dosage of FOXP2, caused by mutation or chromosomal rearrangements, leads to characteristic deficits in coordinating sequences of orofacial movements, impairing speech, producing a disorder known as developmental verbal dyspraxia (DVD) or childhood apraxia of speech (CAS)." (PMID 25781923, 2015). "The Forkhead box protein 2 (FOXP2) mutations in humans lead to developmental verbal dyspraxia (DVD) and lentivirus mediated FOXP2 gene knockdown in zebra finch results in abnormal speech production." (PMID 37107658, 2023). "Affected family members were diagnosed with a severe speech impairment known as developmental verbal dyspraxia (also known as childhood apraxia of speech; OMIM: 602081) and carried a mutation in one copy of their FOXP2 gene." (PMID 26635706, 2015). "The KE phenotype has since been described as childhood apraxia of speech (CAS), which has been linked to disruptive variants within FOXP2, as demonstrated by similarly affected families." (PMID 25411653, 2014). "The expressive language impairment that our patient exhibits resembles the developmental delays (developmental verbal dyspraxia, DVD) that have been found to be associated with mutations in the FOXP2 gene (Forkhead-box P2) which is located on chromosome 7." (PMID 22104167, 2011). "Therefore, a deletion of the cis-regulatory element, which is demonstrated in a patient with developmental verbal dyspraxia, results in FOXP2 haploinsufficiency (monoallelic expression)." (PMID 28887603, 2018).
developmental verbal dyspraxia (continued). "In humans, FOXP2 is involved in a rare form of speech and language disorder with developmental verbal dyspraxia (childhood apraxia of speech or CAS, MIM #602081)." (PMID 29330474, 2018).
speech disorder (29 papers, 2011 to 2025). A term referring to disorders characterized by the disruption of normal speech. "ADHD and DLD share genetic risk loci, including FOXP1 and FOXP2, with rare variants associated with both speech disorders and ADHD." (PMID 41009966, 2025). "FOXP2, the first gene found to be associated with voice and speech disorders, has been the subject of much of the initial functional research centered on its drive for neurological evolution, developmental disorders, and neurodegenerative diseases." (PMID 38702712, 2024). "YY1 and FOXP2 are involved in similar pathways of neural development, and both are associated with speech disorders and autism spectrum disorder." (PMID 37815922, 2023). "There is a connection identified between mutations in the transcription factor FOXP2 gene and speech disorders, and an assumption was made that FOXP2 is responsible for speech and language development in humans." (PMID 32912141, 2020). "The analysis of ClinVar pathogenic variants identified a reported pathogenic variant in FOXP2 (p.Q175delinsQQQQQ) in F47, a known genetic etiology for speech disorders." (PMID 32666661, 2020). "In humans, mutations in FOXP1 and FOXP2 have been implicated in cognitive deficits including intellectual disability and speech disorders." (PMID 30753188, 2019). "Heterozygous FOXP2 mutations cause childhood apraxia of speech (also known as developmental verbal dyspraxia), a severe speech disorder, and most of the affected individuals also show mild cognitive impairments, which are most apparent for the verbal domain." (PMID 30753188, 2019). "Previous theoretical accounts have suggested a role of the thalamus in oro-motor control related to speech, but familial speech disorder (FOXP2) has hitherto been mostly associated with the caudate nucleus." (PMID 27747153, 2016). "We show striking deficits in mice heterozygous for either of two different Foxp2 mutations previously implicated in human speech disorders." (PMID 22412993, 2012). "Notably, the RNA of FOXP2, a transcription factor implicated in neurodevelopment and speech disorders, was differentially regulated- upregulated in some ASD EV lines and downregulated in others." (PMID 40470213, 2025). "However, it is worth noting the shared neurodevelopmental programs controlled by GNAO1 and FOXP2, the most studied monogenic cause of severe speech disorders." (PMID 41387899, 2025). "FoxP2 was reported in 1990 as a putative “speech gene” that binds to the fork head box protein P2 and the autosomal dominant trait, causing a severe and specific speech disorder." (PMID 34827071, 2021). "It was found to be a direct neural target of the human FOXP2 protein, and mutations of FOXP2 and CNTNAP2 were linked to language and speech disorders in ASD." (PMID 28105001, 2016). "FOXP2 plays a role in neurogenesis and is involved in language and speech disorders SEMA5A, which encodes members of the semaphorin family, has been implicated in axonal guidance and is a candidate gene in autism spectrum disorder." (PMID 27483351, 2016). "Haploinsufficiency of FOXP2 usually causes a speech disorder in absence of autistic features, and association of common variants with ASD is controversial." (PMID 30753188, 2019).
breast carcinoma (24 papers, 2015 to 2025). "Specifically, FOXP2 binds to the promoters of genes associated with breast cancer cells, such as e-cadherin and PHF2, and activates their transcription to inhibit EMT." (PMID 38605023, 2024). "Also, elevated miR-199a and depressed FOXP2 expression levels are found to be prominent features of malignant clinical breast cancer and are associated with poor survival." (PMID 27999212, 2017). "Another study showed that MSCs, via upregulating the miR-199 and miR-214, inhibit the expression of the FOXP2 transcription factor in cancer cells to stimulate breast cancer metastasis." (PMID 38022534, 2023). "In breast cancer, it has been found that MSCs inhibit FoxP2 by increasing the expression of mir-214 and mir-199 in these cancer cells, thus increasing the growth, metastasis, and staying in the phenotypic state of cancer stem cells." (PMID 38022534, 2023). "FOXP2/3 had a significantly high AUC value in the detection of breast cancer, with 96.8% or 95.7% in accuracy respectively." (PMID 35614183, 2022). "Our results showed that FOXP2 or FOXP3 had a significantly high AUC value in the detection of breast cancer, with 96.8% or 95.7% in accuracy respectively." (PMID 35614183, 2022). "But the expression of FOXP2 in breast cancer patients has nothing to do with the tumor histological type." (PMID 35614183, 2022). "It was also found that the low transcription levels of FOXP2 in breast cancer patients correlated with poor OS, PFS." (PMID 35614183, 2022). "FOXP2 participates in the process of invasion and metastasis of breast cancer via the TGFβ/SMAD pathway." (PMID 36160018, 2022). "Downregulation of FOXP2 enhances tumor initiation in breast cancers as a putative tumor/metastasis suppressor." (PMID 36203616, 2022). "The results confirmed that the FOXP2-improved survival in breast cancer patients was correlated with the high levels of FOXA2." (PMID 33718155, 2021). "The strong evidence of FOXP2 as a tumor-suppressor role comes from a breast cancer study, in which silencing FOXP2 through miRNA-mediated FOXP2 repression promotes cancer stem cell traits and metastasis in breast cancer cells." (PMID 33718155, 2021). "Same experiments were also performed with HCC1397 cells (representing epithelial breast cancer cells) and MDA-MB-436 cells (representing mesenchymal breast cancer cells) and the similar phenomena of FOXP2 inhibiting the breast cancer cell EMT were observed." (PMID 33718155, 2021). "In breast cancer, MSCs potentiate stemness by inducing microRNA-199a and microRNA-214 expression in cancer cells, which have been shown to repress Forkhead box protein P2 (FOXP2) expression and thus enhance mammary CSC features." (PMID 33530455, 2021). "Both SRPX2 and uPAR were identified as the stimulators of EMT progression in multiple types of cancers including breast cancer, providing a clue to explain the role of FOXP2 as an EMT repressor." (PMID 33718155, 2021). "Together, this study confirmed that in concert with FOXA2, FOXP2 acted as a tumor-suppressor through inhibiting EMT of breast cancer cells." (PMID 33718155, 2021). "Studies have shown that MSCs can promote wist-mediated expression of mir-199a/214 in breast cancer through direct contact with breast cancer cells, thereby inhibiting FOXP2 activity and up-regulating the stem-related pathway in CSCs." (PMID 34001269, 2021). "Then we analyzed the levels of FOXP2 expression in the clinical breast cancer samples (n=394) from TCGA and found that the levels of FOXP2 in all four breast cancer subgroups (Basal, Her2, LumA, and LumB) were lower than that in the normal group." (PMID 33718155, 2021). "This study provided evidence that FOXP2 activated the transcription of its target genes in the maintenance of epithelial characteristics for breast cancer cells." (PMID 33718155, 2021). "For example, its expression is down-regulated in breast cancer, hepatocellular carcinoma, and gastric cancers, in which FOXP2 plays roles as a tumor-suppressor." (PMID 33718155, 2021).
breast carcinoma (continued). "The stable knockdown of FOXP2 expression promoted the mesenchymal phenotype of breast cancer cells, while the overexpression of FOXP2 inhibited the EMT of breast cancer cells." (PMID 33718155, 2021). "Following Western blotting, we confirmed that FOXA2 and FOXP2 interacted physically in breast cancer MCF-7 cells." (PMID 33718155, 2021). "The overexpression of FOXP2 attenuated the mesenchymal phenotype whereas the stable knockdown of FOXP2 promoted EMT in breast cancer cells." (PMID 33718155, 2021). "Another study showed that lncRNATSLNC8 inhibited miR-214-3p/FOXP2 axis to suppress the proliferation and G1/S phase transition of breast cancer cells." (PMID 33312221, 2020). "FOXP2 negatively regulates stem cell-associated factors—such as c-MYC, OCT-4, and CD44—in breast cancer, resulting in a putative tumor/metastasis suppressor." (PMID 31936744, 2020). "FOXP1 has protein-protein interaction with NFAT1 to enhance breast cancer cell motility and FOXP2 is essential in growth arrest of 143 osteosarcoma cells via p21 activation." (PMID 31815635, 2019). "For instance, MSCs were shown to cause aberrant microRNA profile in breast cancer cells, which promotes CSC propagation via repression of FOXP2." (PMID 29670904, 2018). "While FOXP2 is expressed in numerous cell types, its expression has been found to be down-regulated in breast cancer, hepatocellular carcinoma and gastric cancer biopsies." (PMID 29725501, 2018). "In breast cancer a network of microRNAs (particularly miR-199a), whose expression is deregulated by mesenchymal stem/stromal cells, repress FOXP2 expression." (PMID 27224915, 2016). "FOXP2 silencing in breast cancer promoted cancer stem cells and tumor metastasis, while elevated miR-199a and reduced FOXP2 expression correlated with a significantly inferior outcome for patients." (PMID 27224915, 2016). "The ability of FOXP2 to inhibit EMT in breast cancer is dependent on FOXA2." (PMID 38605023, 2024). "Studies have shown that FOXP2 can inhibit the metastasis of breast cancer cells." (PMID 38605023, 2024). "Additionally, FOXP2 has been found to play opposite roles in breast cancer and in triple negative breast cancer." (PMID 36331719, 2023). "Similarly, In this study, database analysis found that the transcription levels of FOXP2 in human breast cancer were lower than in normal tissues, and similar result also was found in our specimen by immunohistochemical staining." (PMID 35614183, 2022). "On the basis of these findings, we conclude that FOXP2 and FOXP3 might act as a potential diagnostic biomarker to differentiate breast cancer from normal normal tissues." (PMID 35614183, 2022). "Furthermore, the stable knockdown of FOXP2 enhanced the metastatic capacity of breast cancer cells in vivo." (PMID 33718155, 2021). "The expression levels of FOXP2 varied among different breast cancer cell lines, in which the epithelial-type cell lines such as MCF-7 and HCC1397 exhibited higher levels of FOXP2 than that of the mesenchymal-type cell lines such as MDA-MB-231, MDA-MB-453, and MDA-MB-436." (PMID 33718155, 2021). "In this study, we found that the levels of E-cadherin relied on FOXP2 in breast cancer cells." (PMID 33718155, 2021). "Together, these results determined that inhibition of FOXP2 could enhance the metastasis of breast cancer cells in vivo." (PMID 33718155, 2021). "In this study, FOXA2-interacting FOXP2 was confirmed to act as an EMT suppressor during metastasis in breast cancer cells, adding a new Fox transcription factor to the list of EMT regulators and also providing a further support of FOXA2’s roles on EMT inhibition." (PMID 33718155, 2021). "To test whether FOXP2 abolished the phenotype of mesenchymal breast cancer cells, we transfected the FOXP2-expression plasmids into MDA-MB-231 cells." (PMID 33718155, 2021).
breast carcinoma (continued). "Together, the results suggested that FOXP2 could inhibit EMT in breast cancer cells by activating transcription of certain genes, such as E-cadherin and PHF2." (PMID 33718155, 2021). "To test whether FOXP2 was required for the epithelial phenotype of breast cancer cells, we used RNA interference strategy to knock down the levels of FOXP2 in MCF-7 cells." (PMID 33718155, 2021). "Together, we proposed that FOXP2 could act as a transcriptional activator through its interaction with FOXA2 in breast cancer cells." (PMID 33718155, 2021). "Based on this data set, we observed a weak correlation between the expressions of FOXA2 and FOXP2 in the samples (R=0.14, p=0.007), while a moderate correlation between their expressions was further found in the subgroup of basal breast cancer especially (n=98, R=0.34, p=0.001)." (PMID 33718155, 2021). "According to functional evidences reported in breast cancer and survey of recent transcriptomic and proteomic analyses of different tumor biopsies, we postulate that FOXP2 dysregulation may play a main role throughout cancer initiation and progression." (PMID 29725501, 2018). "In line with the previously reported oncogenic mechanism (entity “breast cancer”), it might be necessary to determine whether the observed FOXP2 levels concern endogenous HCC cancer stem cells per se, or mesenchymal stem cells prone to HCC homing." (PMID 29725501, 2018). "Functional validation has led to the notion that FOXP2 repression, mediated by microRNAs, was causal to this phenotype and not consequential, at least in breast cancer." (PMID 29725501, 2018). "In breast cancer, miR-199a was also reported to repress FOXP2." (PMID 27999212, 2017). "Furthermore, FOXP2 targets GRP78 in breast cancer to promote tumour proliferation and metastasis." (PMID 36160018, 2022). "FOXP2 therefore might be identified as a suppressor of breast cancer metastasis." (PMID 33718155, 2021). "Noticeably, the oncogenic course might be more complicated as it has been reported in other cancers (see further) that invasiveness was either associated with FOXP2 up-regulation as in prostate cancer or, conversely, with FOXP2 down-regulation as reported for breast cancer." (PMID 29725501, 2018). "As discussed in paragraphs dedicated to breast cancer and colorectal entities, these observations have raised the possibility that FOXP2 might actively be part of a protective network of factors involved in preventing pro-oncogenic processes - at least in some tissues." (PMID 29725501, 2018). "For instance, FOXP2 can inhibit epithelial-mesenchymal transition by activating the transcription of E-cadherin and PHF2 in breast cancer cells." (PMID 36331719, 2023). "In the current study, we identified that FOXP2 interacted with FOXA2, and the expression of FOXP2 was strongly correlated with the epithelial phenotype of breast cancer cells." (PMID 33718155, 2021). "After confirming the interaction between FOXP2 and FOXA2 through Co-IP and immunofluorescence assays, we showed a correlated expression of FOXP2 and FOXA2 existing in clinical breast cancer samples." (PMID 33718155, 2021). "The analysis of clinical samples showed that the FOXP2-improved survival in patients depended on the high expression of FOXA2 in breast cancer, implicating involvement of FOXA2 for FOXP2 performing its functions." (PMID 33718155, 2021). "On the other hand, FOXP2 has also been reported to activate the transcription of genes, such as the protein-tyrosine kinase SYK that is described as a tumor suppressor in breast cancer cells." (PMID 33718155, 2021). "Together, these observations suggested that FOXP2 could bind to the E-cadherin promoter and stimulate the transcription of E-cadherin through the FOXP2-FOXA2 interaction in breast cancer cells." (PMID 33718155, 2021). "In this study, we found that FOXP2 could bind to certain promoters and stimulate the transcription of its target genes such as PHF2 and E-cadherin in breast cancer cells." (PMID 33718155, 2021).